TNFRSF13B (TNF receptor superfamily member 13B)
Description:
Receptor for TNFSF13/APRIL and TNFSF13B/TALL1/BAFF/BLYS that binds both ligands with similar high affinity. Mediates calcineurin-dependent activation of NF-AT, as well as activation of NF-kappa-B and AP-1. Involved in the stimulation of B- and T-cell function and the regulation of humoral immunity.
Synonyms: CD267; TACI; IGAD2; CVID; CVID2; RYZN; TNFRSF14B
Tractability: Antibody: its Gene Ontology location is reachable by antibodies, with high confidence; UniProt predicts a signal peptide or a membrane-spanning region. PROTAC: ubiquitination databases record sites on it.
Gene: Protein-coding gene on chromosome 17 (16,929,816 to 16,972,118, reverse strand). Ensembl gene ENSG00000240505.
Subcellular location: Membrane
Pathways (Reactome):
Immune System: TNFs bind their physiological receptors
Gene Ontology:
Molecular function: protein binding; signaling receptor activity
Biological process: B cell homeostasis; cell surface receptor signaling pathway; hematopoietic progenitor cell differentiation; negative regulation of B cell proliferation
Cellular component: plasma membrane; membrane
Genetic constraint (gnomAD): Loss-of-function variants: 36 observed, 26.1 expected, observed/expected ratio (o/e) 1.38, 90% interval 1.05 to 1.79. The upper end of that interval is the gene's LOEUF score, 1.79, which puts it in group 6 of 6, group 1 being the genes least tolerant of losing a copy. Missense variants: 415 observed, 397.66 expected, observed/expected ratio (o/e) 1.04, 90% interval 0.96 to 1.13. Synonymous variants: 173 observed, 156.47 expected, observed/expected ratio (o/e) 1.11, 90% interval 0.98 to 1.25.
Gene-disease validity (ClinGen):
ClinGen rates the evidence that TNFRSF13B causes each of these diseases.
immunodeficiency, common variable, 2 (autosomal recessive): Definitive.
Homologues: Orthologues: chimpanzee TNFRSF13B (99% identical), dog TNFRSF13B (69% identical), guinea pig TNFRSF13B (57% identical), rabbit TNFRSF13B (55% identical), pig TNFRSF13B (52% identical), rat Tnfrsf13b (46% identical), mouse Tnfrsf13b (45% identical).
Diseases named in the same sentence as TNFRSF13B in open-access papers:
TNFRSF13B is named in the same sentence as 139 diseases in open-access papers, as found by Europe PMC text mining. Sharing a sentence is not in itself a finding about the gene and the disease. The quoted sentences say what the papers report.
myeloma (39 papers, 2009 to 2025). "The APRIL signaling pathway was active between monocytes and neutrophils (TNFSF13), with its receptor (TNFRSF13B) in high-risk UPPRS myeloma cells." (PMID 37047654, 2023). "A combined analysis of African and European ancestry populations identified a missense variant (rs34562254) in TNFRSF13B associated with multiple myeloma risk." (PMID 35524261, 2022). "TNFRSF13B expression on myeloma cells of MGUS and MM patients predicts a higher risk of poor prognosis." (PMID 34150664, 2021). "Specifically, TNFSF13B expression had close interactions with macrophage marker genes, namely, TLR and S100A9 genes; their receptor genes, TNFRSF13B and TNFRSF17, showed significant associations with the myeloma-related genes CD38, SDC1, and MYEOV." (PMID 34150664, 2021). "Using primary myeloma cells of MM patients, we ascertained that TNFRSF13B transduced ligand signals to activate the canonical NF-κB pathway, ultimately allowing cell proliferation." (PMID 34150664, 2021). "Nevertheless, the correlations of TNFRSF13B with myeloma-related genes and shorter survival, alongside TNFRSF13B mutations that thwarted MM advancement, indicate the importance of TNFSF13B signal in the MM prognosis of patients." (PMID 34150664, 2021). "Interestingly, our finding suggested the involvement of the proteasome inhibitor-Bortezomib in both canonical NF-κB and MAPK/p38 signaling pathways, highlighting TNFRSF13B as a big player in S100A9-associated myeloma progression." (PMID 34150664, 2021). "Compared to the MGUS, MM patients were characterized by an evident rise in MYEOV+ myeloma cells, in which a clear upregulation of TNFSF13B receptors, TNFRSF13B and TNFRSF17, was detected." (PMID 34150664, 2021). "Our results demonstrated that S100A9 administration upregulated TNFRSF13B and TNFRSF17 surface expressions on myeloma cells, indicating crosstalk between TLR activation and TNFSF13B signaling." (PMID 34150664, 2021). "Both TNFRSF13B and TNFRSF17 surface expressions were upregulated on patient myeloma cells versus plasma cells from the healthy controls." (PMID 34150664, 2021). "Emphasizing the validity of this strategy, four of the top six targets by our ranking either already have FDA-approved therapeutics or are being clinically investigated in myeloma: BCMA (TNRFSF17 gene), TACI (TNFRSF13B), Integrin beta-7 (ITGB7), and CS-1/SLAMF7 (SLAMF7)." (PMID 35840578, 2022). "In conclusion, myeloid-derived S100A9 can enhance TNFSF13B/TNFRSF13B expression on myeloma cells, stimulating both canonical and non-canonical NF-κB pathways and thereby fuels tumor cell proliferation." (PMID 34150664, 2021).
Autoimmunity (35 papers, 2013 to 2025). The occurrence of an immune reaction against the organism's own cells or tissues. "This points towards TNFRSF13B as a considerable risk gene for antibody deficiency and autoimmunity by the factor of 3.4x." (PMID 34975878, 2021). "As already demonstrated CVID patients carrying TNFRSF13B heterozygous mutations had a higher prevalence of autoimmunity compared with patients with wild-type TNFRSF13B (61.5% versus 23%, p = 0.005)." (PMID 27123465, 2016). "Nevertheless, it may be hypothesized that the TNFRSF13B variant acts as a genetic modifier, enhancing autoimmunity, which appears more pronounced in the mother." (PMID 40719110, 2025). "Most of the candidate variants in TNFRSF13B found in this study have been repeatedly associated with some degree of antibody deficiency, compromised B cell function, higher risk of developing autoantibody-mediated autoimmunity and/or lymphoproliferation." (PMID 34975878, 2021). "Notably, CVID patients heterozygous for the TNFRSF13B variant have a higher risk of developing autoantibody-mediated autoimmunity than those with homozygous mutations." (PMID 31921101, 2019). "Thus, by inhibiting natural antibody secretion (IgM and IgA) and favoring adaptive antibody responses, TNFRSF13B diversity establishes varying susceptibility to infection, autoimmunity, immunodeficiency, and excessive inflammatory reactions to transplantation and perhaps to pathogens as well." (PMID 34283811, 2021). "TNFRSF13B/TACI defects have been associated with CVID pathogenesis and/or phenotype, especially the development of benign lymphoproliferation and autoimmunity." (PMID 23956760, 2013). "Indeed, TNFRSF13B mutants are associated with common variable immune deficiency (CVID) and autoimmunity." (PMID 34111031, 2021). "The negative regulatory role of TACI has also been evident in human immune deficiency, as patients with CVID who carry heterozygous TNFRSF13B mutations are more likely to have lymphoid hyperplasia and autoimmunity." (PMID 30333819, 2018). "TACI mutations are not per se causative of the disease; however, certain TNFRSF13B mutations can predispose CVID patients to autoimmunity and lymphoproliferation." (PMID 39873967, 2025).
common variable immunodeficiency (33 papers, 2006 to 2025). "Pathogenic variants in TNFRSF13B are associated with common variable immunodeficiency (CVID) [OMIM# 240500], thus this variant was reported as a primary finding based on possible clinical overlap with the participant's history of recurrent infection." (PMID 41346656, 2025). "Approximately 10% of patients with common variable immunodeficiency carry mutations in the TNFRSF13B, and TNFRSF13B-knockout mice display symptoms of systemic lupus erythematosus-like autoimmune diseases." (PMID 35524261, 2022). "Common variable immunodeficiency and IgA deficiency in humans and mice have been associated with TNFRSF13B null and dominant-negative mutations." (PMID 34111031, 2021). "One of our studies showed that all of the patients with TNFRSF13B mutations and common variable immunodeficiency examined also had IgA deficiency, and that 1 IgA-deficient patient also had a TNFRSF13B mutation." (PMID 34111031, 2021). "Mutations in TNFRSF members can also lead to common variable immunodeficiency (CVID): approximately 9 % of patients carry one or two variant alleles of TNFRSF13B (encoding TACI) and a few patients carry biallelic mutations of TNFRSF13C (encoding BAFF-R)." (PMID 27435189, 2016). "Mutations in TNFRSF13B have been identified in common variable immunodeficiency." (PMID 37273692, 2023). "Heterozygous and biallelic variants in TNFRSF13B cause a form of common variable immunodeficiency (CVID2; MIM: 240500), characterized by hypogammaglobulinemia and recurrent infections, including otitis media, respiratory tract infections, and gastrointestinal tract infections." (PMID 31467394, 2019). "In addition, germ-line mutations in TNFRSF13B were reported in cases of common variable immunodeficiency (CVID; MIM # 607594) and selective IgA deficiency (IGAD; MIM # 137100)." (PMID 22558069, 2012). "Two main PADs have been linked with TNFRSF13B mutations: common variable immunodeficiency (CVID) and selective immunoglobulin A deficiency (sIgAD)." (PMID 40959164, 2025). "Individuals who carry rare loss-of-function variants in TNFRSF13B are predisposed to common variable immunodeficiency (CVID), a condition defined by low IgG and IgA levels due to stalled development of mature B-cells and plasma cells." (PMID 39103364, 2024). "Mutations in transmembrane activator and calcium modulator and cyclophilin ligand interactor (TACI, TNFRSF13B) have been found in a subset of patients with IgA deficiency, but also in patients with common variable immunodeficiency (CVID)." (PMID 35186163, 2021). "The heterozygous, homozygous, and compound heterozygous variants in TNFRSF13B lead to common variable immunodeficiency (CVID) or selective IgA deficiency (OMIM: 240500), that are characterized by susceptibility to recurrent infections with many different infectious agents." (PMID 39062917, 2024). "Case 7 was diagnosed with common variable immune deficiency (CVID), as she was found to have a class 5 variant in TNFRSF13B (p.A181E)." (PMID 38006337, 2023). "Among identified genetic defects, mutations in transmembrane activator and calcium-modulator and cyclophilin ligand interactor (TACI, TNFRSF13B) have been reported in 7–10% of Common Variable Immunodeficiency (CVID) patients and 13% of SIgAD carried at least one mutated TNFRSF13B allele." (PMID 35056437, 2022). "Their importance is highlighted by common variable immunodeficiency (CVID) and selective IgA deficiency (SIgAD) linked to mutations in TNFRSF13B, encoding TACI." (PMID 34978077, 2022). "The Transmembrane Activator and Calcium modulator ligand Interactor (TACI), encoded by TNFRSF13B/TACI gene, is mutated in some patients with Common Variable Immunodeficiency (CVID) and IgA Deficiency (IgAD)." (PMID 30090215, 2018). "Dominant-negative effect has been previously discovered in many genes and diseases such as Keap1 in lung cancer and TNFRSF13B in CVID (common variable immunodeficiency)." (PMID 25425654, 2014).
common variable immunodeficiency (continued). "Finally, the mother possesses a variant in the TNFRSF13B gene, which encodes the transmembrane activator and calcium-modulating cyclophilin ligand interactor (TACI), a receptor crucial for B-cell function and immunoglobulin production and associated with common variable immunodeficiency (CVID)." (PMID 40719110, 2025). "Mutations in TNFRSF13B, which encodes a protein called TACI are typically linked to common variable immunodeficiency (CVID) and not classically associated with autoinflammatory syndromes." (PMID 40995171, 2025). "An association of common variable immunodeficiency (CVID) and SIgAD with mutations of incomplete penetrance in TNFRSF13B has been reported, but this finding could not be replicated in a larger SIgAD cohort." (PMID 39241920, 2024).
Immunodeficiency (28 papers, 2009 to 2026). Failure of the immune system to protect the body adequately from infection, due to the absence or insufficiency of some component process or substance. "The presence of a second TNFRSF13B mutation, HLA class II markers, or multiple single nucleotide variants in patients helps to explain the incomplete penetrance of immunodeficiency in carriers of TNFRSF13B mutations." (PMID 40959164, 2025). "A frameshift variant in TNFRSF13B, consistent with a combined immunodeficiency phenotype, was identified; SCID was diagnosed by integrating this genetic result with the patient’s clinical and immunologic findings." (PMID 41426715, 2025). "Interestingly, TNFRSF13B/TACI mutations have also been reported in patients with IgA deficiency (IgAD), namely the most common immunodeficiency in the Western world, with a prevalence of approximately 1 in 700 individuals." (PMID 34441032, 2021). "This panel screens for major monogenic immunodeficiencies, including predominantly antibody deficiencies (e.g., TNFRSF13B/TACI, ICOS, CD19, IKBKB), combined immunodeficiencies, phagocytic and innate immunity defects, and complement pathway deficiencies." (PMID 40918823, 2025). "In this family, the synergistic interaction of TNFRSF13B/TACI and TCF3 mutations resulted in a severe immunodeficiency and systemic lupus erythematosus (SLE) in the proband." (PMID 30323807, 2018). "Similar dualities for the STAT1 (M600555), TNFRSF13B (M6049097), and TICAM1 (M607601) genes may apply since the first two are associated with immunodeficiency disorders and the last confers susceptibility to encephalopathy from herpes virus infection." (PMID 37504295, 2023). "Using heat maps to depict variations from normal in patients with known mutations in TNFRSF13B, CTLA4, and CARD11, we asked whether we could identify trends within defined cellular populations that might be relevant to the genetic pathogenesis of their immunodeficiency." (PMID 31572362, 2019). "The observation that TNFRSF13B mutations are present not only in CVID patients, but also in IgAD cases suggests that modifier genes as well as their combination with other genetic or environmental factors may play an important role in the development of the immunodeficiency phenotype." (PMID 30090215, 2018). "Although the first of them have ascribed a pathogenic role of TNFRSF13B/TACI alterations in CVID, further studies suggested that these mutations might represent modifiers of the disease, since they are also present in healthy individuals, without any evidence of immunodeficiency." (PMID 23956760, 2013).
lupus (27 papers, 2008 to 2025). "It is worth mentioning that TNFRSF13B/TACI knockout mice develop lymphoproliferation, lupus-like nephritis, and elevated levels of circulating autoantibodies." (PMID 23956760, 2013). "Until now, only one study has analyzed the role of TNFRSF13B/TACI in systemic lupus erythematosus but did not reveal any deleterious or disease-associated mutations into the coding region of the gene." (PMID 23956760, 2013).
antibody deficiencies (17 papers, 2013 to 2025). "Variants in the gene encoding TACI (TNFRSF13B) have been identified since 2005 in patients with predominantly antibody deficiency (PAD) employing a candidate gene approach based on single-gene knockout mice." (PMID 40959164, 2025). "Further studies are needed to unravel the additional genetic and environmental factors acting in concert with biallelic genetic alterations in TNFRSF13B to give rise to antibody deficiencies in humans." (PMID 27123465, 2016). "However, TNFRSF13B variants are most often associated with antibody-deficiency phenotypes (e.g., CVID), and a single heterozygous frameshift is unlikely by itself to account for a classical SCID presentation." (PMID 41426715, 2025). "In conclusion, TNFRSF13B genetic screening of antibody deficiencies may allow the identification of mutational patterns." (PMID 27123465, 2016). "Thus, we suggest that the presence of TNFRSF13B/TACI defects might predispose to immune-mediated diseases (ranging from benign lymphoproliferation to overt antibody deficiency) depending on the interaction with other immune gene defects and/or specific environmental factors." (PMID 23956760, 2013). "Moreover, the spectrum of genetic variants identified in our patients—including TNFRSF13B, DOCK8, RAG1, and LRBA—closely resembles the mutational landscape reported in prior studies of CVID and other antibody deficiencies." (PMID 40993545, 2025). "The most frequent main genetic causes of predominantly antibody deficiencies in children infected with SARS-CoV-2 were BTK (n = 41), NFKB2 (n = 4), TNFRSF13B (n = 3), PIK3CD (n = 3), and PIK3R1 (n = 2)." (PMID 37559153, 2023). "For instance, mutations in TNFRSF13B, NFKB1, NFKB2, CTLA4 and STAT3 are indications for the early molecular diagnosis of patients with predominantly antibody deficiency such as predominantly antibody deficiencies." (PMID 37033178, 2023). "Pathogenic variants in CTLA4, LRBA, TNFRSF13B (TACI), DOCK8, RAG1, PRF1, PIK3CD, IKZF1, and PRKDC have been identified in patients with AICs and PIDs, often associated with other clinical features such as lymphoproliferation, splenomegaly, and immunologic abnormalities such as hypogammaglobulinemia." (PMID 40993545, 2025).
autoimmune disease (13 papers, 2012 to 2025). A disorder resulting from loss of function or tissue destruction of an organ or multiple organs, arising from humoral or cellular immune responses of the individual to their own tissue constituents. "Abnormal TNFRSF13B signalling has been related to autoimmune disorders." (PMID 35524261, 2022).
breast carcinoma (11 papers, 2008 to 2023). "TNFRSF17 and TNFRSF13B, members of the tumor necrosis factor receptor superfamily, are primarily involved in the maturation of B lymphocytes and are associated with tumor growth and invasiveness and may serve as therapeutic targets in breast cancer." (PMID 35087563, 2021). "In breast cancer several TNF receptor superfamily (TNFRSF) members BAFF, APRIL, BCMA (TNFRSF17) and TACI (TNFRSF13B) have been associated with tumor initiation and progression." (PMID 33816291, 2021). "TNFRSF13B is the significant marker gene in B cells for breast cancer." (PMID 36479102, 2022). "Additionally, it has been confirmed that silencing of the cytokine receptor TNFRSF13B might serve as a new therapeutic target for triple-negative breast cancer, as it could result in significant death in breast cancer cell lines." (PMID 36479102, 2022). "Interestingly, TNFRSF13B (TACI) mRNA level were of prognostic relevance in breast cancer patients." (PMID 33816291, 2021). "We here comprehensively study the expression of the TACI (transmembrane activator and CAML interactor, TNFRSF13B) on platelets of breast cancer patients." (PMID 33816291, 2021).
lymphoma (9 papers, 2007 to 2025). A malignant (clonal) proliferation of B- lymphocytes or T- lymphocytes which involves the lymph nodes, bone marrow and/or extranodal sites. "Moreover, patients with the non-missense deleterious mutations had a higher susceptibility to cancer development (mainly due to lymphoma and carcinomas) in comparison to cases with missense TNFRSF13B mutations (27.2% vs. 7%, P = 0.001)." (PMID 40959164, 2025). "Using exome sequencing, they identified six recurrent, rare, and potentially deleterious variants within 5 kb of lymphoma-associated GWAS loci in 75 MM cases (BTNL2, EOMES, TNFRSF13B, IRF8, ACOXL, TSPAN32)." (PMID 41300981, 2025).